INS (insulin)
Diseases named in the same sentence as INS in open-access papers (continued):
Sharing a sentence is not in itself a finding about the gene and the disease.
Hyperglycemia (continued). "The hyperglycemia was then controlled by the AIIS by means of a sharp and sustained increase in the insulin infusion rate, that corrected glycemia after a TS of 60 minutes." (PMID 20642855, 2010). "NF-κB is activated by TNFα and IL-1 next to hyperglycemia, AGEs, ANG-II, oxidized lipids, and insulin." (PMID 20634940, 2010). "For example, inflammation, free fatty acids (FFAs), and hyperglycemia in pancreatic β cells elicit activation of the UPR, leading to decreased insulin mRNA expression and inhibition in the insulin signaling." (PMID 20808779, 2010). "Much has been written in recent years about the potential role of hyperglycemia on admission and during the ICU stay on outcomes in ICU patients and the need for tight control of glucose concentrations using insulin." (PMID 20132545, 2010). "Furthermore, although long-term exercise may lead to improved insulin sensitivity and therefore reduced plasma insulin levels, in rats, it does not lead to extensive weight loss and/or hyperglycemia." (PMID 20339560, 2010). "The obese rats exhibit mild fasting hyperglycemia, but marked hyperglycemia during an oral glucose tolerance test (OGTT), with elevated fasting insulin levels and blunted insulin responses." (PMID 20231880, 2010). "Hyperglycemia in SDT rat is spontaneously developed, predominantly due to an insulin secretory defect resulting from pathological damage to the pancreatic islets, especially β-cells." (PMID 20508774, 2010). "Insulin and bioavailable insulin-like growth factor-I (IGF-I) are possible links between glucose and cancer; hyperglycaemia induces elevation of these hormones that stimulate tumour growth." (PMID 20027213, 2009). "Overall, even though the strains exhibited specific patterns of regulations of glucose homeostasis and insulin secretion, three weeks of HFD feeding generally induced profound hyperglycemia and hyperinsulinemia." (PMID 18301746, 2008). "Second, to model uncontrolled diabetic conditions and mechanistically elucidate the direct impact of chronic hyperglycemia on CNS pathologies, insulin intervention was not implemented in our STZ-induced T1D mice." (PMID 41484634, 2026). "One year later she developed hyperglycemia and ketosis and showed no glycemic effect from SC insulin." (PMID 41472947, 2026). "Here, using a sensitive and specific glucagon assay, we show that exogenous GLP-2, compared to placebo, increases glucagon secretion only slightly during euglycemia, and not during hyperglycemia or insulin-induced hypoglycemia in healthy men." (PMID 41541287, 2026). "Routine blood tests indicated hyperglycaemia following STZ treatment that was confirmed post-mortem, with STZ-diabetic rats indicating a 50% increase in plasma glucose (p < 0.001) coupled with an 80% decrease in plasma insulin concentrations (p < 0.001)." (PMID 41590669, 2026). "In this case, however, blood glucose remained around 6 mmol/L via continuous insulin infusion, without hyperglycemia or glycosuria, thereby ruling out osmotic diuresis." (PMID 41559973, 2026). "After a 4-week therapeutic period, SWEPFT markedly ameliorated hyperglycemia, as evidenced by reduced body weight (BW), fasting blood glucose (FBG), and glycated serum protein (GSP) and improved insulin sensitivity/resistance indicators (HOMA-IS/IR) and β-cell function (HOMA-β)." (PMID 41517209, 2026). "Compared with patients without PDAC, patients with PDAC showed severe hyperglycemia with impaired insulin secretion before surgery." (PMID 41593307, 2026). "Compared to placebo, GLP-2 increased glucagon secretion slightly during euglycemia, and not during insulin-induced hypoglycemia or hyperglycemia." (PMID 41541287, 2026). "In non-insulin treated patients with T2D, CGM has been shown to facilitate in-depth evaluation of the effect of local steroids on glucose levels and events of severe hyperglycemia following steroid administration." (PMID 41601933, 2026).
Hyperglycemia (continued). "Collectively, our findings show that supraphysiological levels of GLP-2 slightly but significantly increase glucagon secretion during euglycemia and not during insulin-induced hypoglycemia or hyperglycemia, in lean, young, healthy men." (PMID 41541287, 2026). "While this approach avoids the confounding effects of exogenous insulin and effectively isolates hyperglycemia-induced mechanisms, it does not fully recapitulate the clinical scenario where the majority of T1D patients are under insulin therapy." (PMID 41484634, 2026). "Exogenous GLP-2 increased glucagon secretion slightly during euglycemia and not during insulin-induced hypoglycemia or hyperglycemia in healthy young men." (PMID 41541287, 2026). "The stimulation of pancreatic SSTR-5 suppresses insulin secretion, which, combined with negative effects on incretin hormone secretion, leads to pasireotide-induced hyperglycemia." (PMID 40283624, 2025). "This algorithm provides automated basal insulin adjustments at 5 min intervals, continuously adjusting insulin delivery based on real-time CGM (rtCGM), and automatic correction bolus delivery in cases of incipient hyperglycemia." (PMID 41010993, 2025). "Indeed, the evidence presented in this study suggests the potential of M. charantia to reduce hyperglycaemia based on reduced FBG, insulin, HbA1c and HOMA-IR in individuals living with prediabetes and T2D." (PMID 41280283, 2025). "Subsequently, the patient was managed with intravenous insulin and insulin degludec/liraglutide injection, but neither of them stabilized the alternating episodes of hypoglycemia and hyperglycemia." (PMID 41234224, 2025). "Though not directly measured in the present study, insulin is secreted in ~4 min pulses that are amplified in response to hyperglycemia, consistent with these findings and the proposed model." (PMID 39936989, 2025). "It should not be forgotten that hyperglycemia in tissues where glucose uptake is insulin-independent (brain, liver, kidneys, erythrocytes, leukocytes, platelets, lens of the eye, placenta) is more likely to cause metabolic disturbances." (PMID 40362167, 2025). "We report on six cases with different types of IR that responded well to dapagliflozin as an add‐on therapy, after periods of struggling with the control of hyperglycemia using insulin alone or other antidiabetes medications, without complications." (PMID 41424588, 2025). "A titration upwards to 75 U of long-acting insulin and around 100–110 U of rapid-acting insulin was needed, without preventing hyperglycemia up to 25 mmol/L (450 mg/dl)." (PMID 40491591, 2025). "In addition, long-term exercise can improve insulin sensitivity and vascular endothelial function, reducing the inhibition of BDNF expression by hyperglycemia." (PMID 40933306, 2025). "The findings of this study suggested that the lack of insulin signalling without hyperglycaemia in mice did not adversely affect bone density." (PMID 40564223, 2025). "Hyperglycemia can independently induce diacylglycerol (DAG) synthesis, which activates PKC (protein kinase C), which in turn inhibits the PI3-kinase/AKT pathway and reduces eNOS phosphorylation and NO production in response to insulin." (PMID 40871683, 2025). "PBR elicited a greater insulin response in T2DM subjects (3199 ± 1273 mU/L·min) than in healthy controls (1980 ± 568 mU/L·min), suggesting a compensatory insulin secretion in response to hyperglycemia." (PMID 40509433, 2025). "First, prenatal saccharin consumption resulted in disruption of glucose homeostasis, leading to glucose intolerance at weaning, as reflected on the increased time spent on hyperglycaemia in the GTT test, as in the reduced efficacy of insulin observed in the ITT test." (PMID 40524248, 2025). "For individuals with type 1 diabetes, where the body does not produce insulin, low-GI foods can help reduce the frequency of postprandial hyperglycemia and the amount of insulin needed to control blood sugar after meals." (PMID 40026940, 2025).
Hyperglycemia (continued). "Unlike previous studies, which have primarily focused on insulin therapy for managing hyperglycemia in hospitalized patients, our study highlights the efficacy and safety of oral hypoglycemic agents as an alternative treatment strategy." (PMID 40901501, 2025). "Close monitoring is recommended if SU administration is performed before the return of genetic testing to ensure hypo- or hyperglycemia is not occurring with a low threshold for switching back to insulin-based therapy if needed." (PMID 40309172, 2025). "Inappropriately drawn labs showing hyperglycemia when none was actually present mistakenly directed treatment towards use of intravenous insulin, leading to hypoglycemia." (PMID 41393585, 2025). "It is described that propofol can reduce sympathetic nerve activity, resulting in blockade of catecholamine release ultimately not affecting insulin secretion and avoiding acute hyperglycemia." (PMID 39883678, 2025). "In T1DM, the lack of endogenous insulin eliminates its inhibitory effect on pancreatic α-cells, leading to increased glucagon secretion even during hyperglycemia." (PMID 40822953, 2025). "The role of insulin signaling in DM1 is further supported by clinical trials using metformin, which has shown promising effects on exercise capacity and mobility in DM1 patients and is established as an effective treatment for hyperglycemia in DM1." (PMID 41383381, 2025). "Although we found an inhibitory action of fenofibrate on insulin secretion in human pancreatic islets under conditions that resemble type 1 diabetes (inflammation and hyperglycaemia), this did not relieve beta cell stress but instead induced cell death." (PMID 39477880, 2025). "Gradual insulin titration has been reported to be effective in controlling hyperglycemia without hypoglycemic events." (PMID 41480351, 2025). "One key limitation of the present study was that the effects of metformin and insulin treatment on one‐carbon metabolism and fetal outcomes were only assessed in Restricted animals, and these animals did not develop hyperglycaemia." (PMID 40859436, 2025). "For example, the DIGAMI study demonstrated that intensive insulin therapy lowered overall mortality in AMI patients with stress hyperglycemia, independent of their diabetic status." (PMID 40303637, 2025). "Moreover, in the developing pancreas and under certain conditions, such as pregnancy and hyperglycemia, pancreatic α-cells can induce GLP-1 production, which induces insulin production and β-cell regeneration." (PMID 40014427, 2025). "Another challenge during PA and instances of hyperglycaemia is that some AID systems do not restrain insulin delivery effectively enough and/or they continue to give automatic insulin correction doses during PA, even if a higher glucose target is set." (PMID 39653802, 2025). "Nevertheless, during long-lasting hyperglycemia, the insulin-IR neuronal proportion did not change in the ileum and significantly decreased in the colon of diabetic rats." (PMID 40497986, 2025). "Furthermore, concerns remain regarding risks of fluid overload, hypoglycemia induced by insulin therapy in DKA management, and rebound hyperglycemia in hypoglycemia correction, highlighting the need for a critical synthesis of available evidence." (PMID 41262789, 2025). "On the other hand, blood glucose levels were hardly affected by these drugs, indicating that the hyperglycemia in streptozotocin-induced T1D is mainly due to the lack of primary action of insulin on peripheral glucose uptake." (PMID 40149735, 2025). "To this end, we use a short-term (30–50 days) gestation model complicated by hyperglycemia, without insulin replacement and obtained by chemical induction of beta cell death." (PMID 40563978, 2025). "The negative impacts of hyperglycemia on kidney function are likely part of a complex interplay of the kidney’s ability to maintain glucose homeostasis and insulin as its main regulator." (PMID 40272476, 2025).
Hyperglycemia (continued). "In case 1, the insulin dose was not reduced, as the SGLT2i was introduced during a state of hyperglycemia." (PMID 40704640, 2025). "For most hospitalized patients with DM2 and without HF, basal-bolus insulin, or in the case of mild hyperglycemia, DPP4i, remains the standard of care." (PMID 39816910, 2025). "With our findings of ad libitum and fasting hyperglycemia, coupled with decreased fasting insulin and c-peptide in SCD mice at 20 weeks of age, suggestive of developing pancreatic β cell dysfunction, we next assessed pancreatic insulin content." (PMID 40294908, 2025). "Elevated insulin levels can increase IGF-1 expression, which subsequently enhances androgen synthesis in the ovaries, while hyperglycemia may concurrently activate AMPK, further affecting androgen production." (PMID 40776915, 2025). "Toxic effects of hyperglycemia on ovaries and/or increased IGF-1 levels might potentiate the effects of insulin on ovaries in women with prediabetes." (PMID 41384021, 2025). "In this case, however, the marked hyperglycemia and the brief period of suppressed insulin secretion did not lead to sustained autoimmune activity or permanent β-cell dysfunction." (PMID 40351955, 2025). "The risk of onset was elevated in parallel with HbA1c, even with treatment of hyperglycemia not dependent on insulin therapy, with no clear threshold." (PMID 41129145, 2025). "Defects in mitochondrial function impair this metabolic coupling, and insufficient insulin fails to compensate the demand for insulin, ultimately hyperglycemia occurs." (PMID 40018267, 2025). "Gluconeogenesis also contributes to hyperglycemia in T2DM, and these patients exhibit a defect in insulin action, a condition known as insulin resistance, which may impact hepatic glucose regulation." (PMID 40806011, 2025). "The exact mechanism for dabrafenib induced hyperglycaemia has not been elucidated, given that glucose control mediated by insulin is primarily through the PI3K pathway rather than MAPK/ERK." (PMID 39671021, 2025). "Stress hyperglycemia is temporary and does not match the patient's persistent hyperglycemia, requiring long-term insulin treatment." (PMID 40901503, 2025). "Moreover, postprandial hyperglycemia in GDM can enter the fetal circulation, stimulating fetal pancreatic β-cell proliferation and insulin secretion, leading to fetal hyperinsulinemia." (PMID 40797060, 2025). "K ATP channels are metabolic sensors responsible for regulating hyperglycemia by controlling insulin secretion, making this regulation mediated by TIM highly novel." (PMID 41009376, 2025). "It is interesting that the NAFLD group showed a significant increase in HOMA‐IR with hyperglycemia, but no significant increase in insulin levels." (PMID 41306343, 2025). "While 8 mg dexamethasone led to a significant increase in blood glucose levels (peaking at 128.93 ± 4.42 mg/dL, p < 0.001), no patients required insulin therapy or prolonged hospital stays due to hyperglycemia." (PMID 40225449, 2025). "Insulin infusions for managing hyperglycemia were administered to two patients in each of the ARB and non-ARB groups." (PMID 40564161, 2025). "During hyperglycemia, glucose uptake in platelets is increased since this uptake in these cells is not insulin-mediated." (PMID 40362167, 2025). "In MASLD, insulin fails to suppress gluconeogenesis and glucose output from the liver, yet continues to increase lipid synthesis, leading to hyperglycemia and hypertriglyceridemia." (PMID 40006091, 2025). "Mice lacking HMGCR in beta-cells (b-KO) exhibited hyperglycemia and low insulin levels due to decreases in both beta-cell mass and insulin secretion." (PMID 39775321, 2025).
Hyperglycemia (continued). "However, under the cytotoxic effects of prolonged hyperglycemia, both PDX1 and insulin levels decreased." (PMID 40405977, 2025). "Known predisposing factors for autoimmunity positivity in women with hyperglycemia during pregnancy include normal or low pre-pregnancy weight, younger age, low weight gain during pregnancy, the need for insulin therapy, and no family history of T2DM." (PMID 41020242, 2025). "Taken together with the STZ results, the findings demonstrate that cognitive outcomes are shaped by metabolic stress driven by insulin resistance, rather than hyperglycemia being the primary factor." (PMID 40964391, 2025). "These mediators promote hepatic gluconeogenesis, impair insulin secretion, and induce peripheral insulin resistance, leading to transient hyperglycemia independent of chronic glycemic status." (PMID 40303637, 2025). "The hyperglycaemia challenge experienced in the study protocol would not have been feasible to replicate in a control group with intact endogenous insulin secretion." (PMID 41057689, 2025). "Hyperglycemia during the night was due to carbohydrate intake without bolus insulin administration or an inappropriate dose of bolus insulin, although she had received nutritional therapy repeatedly." (PMID 40822948, 2025). "For example, inappropriate glucagon secretion contributes to hyperglycemia, whereas impaired somatostatin signaling fails to adequately suppress glucagon and insulin secretion." (PMID 40919135, 2025). "While prior studies reported no hyperglycemia worsening, our results highlight the need for enhanced monitoring and dynamic insulin titration to prevent attenuation of survival gains." (PMID 41375876, 2025). "The resultant lack of insulin triggers a cascade of metabolic derangements, including hyperglycemia, dehydration, metabolic acidosis, and ketosis, which is characterized by elevated ketone levels in the blood or urine (serum ketone concentration >3.0 mmol/L)." (PMID 40125203, 2025). "DM is characterized by a lack of insulin, leading to high blood glucose levels, known as hyperglycemia." (PMID 40489503, 2025). "A period of extreme hyperglycemia and low insulin secretion does not guarantee the presence of ketoacidosis." (PMID 38895272, 2025). "Time-course analysis of blood glucose and insulin levels revealed normal glucose clearance and insulin secretion in awake and Hypnorm-sedated conditions, whereas isoflurane-anesthetized mice failed to mount an insulin response despite persistent hyperglycemia." (PMID 41253816, 2025). "When compensation is only partially functional, due to lack of sufficient insulin reserves, maternal hyperglycemia and GDM ensue." (PMID 40235646, 2025). "This case demonstrates that, even in non-diabetic patients, capivasertib can lead to severe hyperglycemia, and early detection combined with prompt initiation of continuous insulin infusion is highly effective." (PMID 41399756, 2025). "In 103 patients with multiorgan failure on insulin for hyperglycaemia, CGM had acceptable bias and MARD and no hypoglycaemia." (PMID 41146739, 2025). "The daily dosage of basal insulin was higher in the GCK-hyperglycemia group in the first and second, but not third trimester." (PMID 41409604, 2025). "Few randomized controlled trials have compared insulin vs noninsulin treatments for managing hyperglycemia in hospitalized patients with DM2 and noncritical illnesses." (PMID 39816910, 2025). "During pregnancy, maternal hyperglycemia stimulates the developing fetal pancreas to increase insulin secretion, because maternal insulin does not cross the placenta." (PMID 40077697, 2025). "Clinical studies have shown that SGLT2i-induced beneficial effects in CKD and CVD/HF patients are independent of hyperglycemia, sex, and insulin secretion/sensitivity." (PMID 40799827, 2025).